SIRT6 (sirtuin 6)
Diseases named in the same sentence as SIRT6 in open-access papers (continued):
Sharing a sentence is not in itself a finding about the gene and the disease.
atherosclerosis (continued). "The principal finding of the present study is that we demonstrate that SIRT6 reduces atherosclerotic lesion formation in a murine model of atherosclerosis through attenuating endothelial dysfunction and vascular inflammation." (PMID 27249230, 2016). "Using the commercial Ingeniuty Pathway Analysis (IPA) software analysis, we found that atherosclerosis signaling pathway was the second one among the 12 top pathways influenced by Sirt6 knockout." (PMID 27045575, 2016). "The downregulation of Sirt6 in atherosclerotic plaques prompted us to study its roles in the development of atherosclerosis." (PMID 27045575, 2016). "The E3 Ubiquitin Ligase ITCH modulates lipid metabolism impacting on atherosclerosis progression independently from effects on myeloid cells polarization through control of SIRT6 and SREBP2 ubiquitination." (PMID 25777360, 2015). "In this study we report on the association of the UCP5, SIRT6 and SIRT5 gene variants with carotid plaque, a surrogate marker of atherosclerosis." (PMID 22087257, 2011). "The combination of inflammation, cellular aging, and high LDL cholesterol constitutes a vicious cycle of atherosclerosis, and SIRT6 may stop this cycle." (PMID 40710369, 2025). "In addition, our study identified serum SIRT6 as an independent biomarker for assessing the severity of coronary artery lesions in older adults, with the optimal cutoff value for classifying atherosclerosis and CAD being 546.384 pg/mL." (PMID 39851250, 2025). "SIRT6 plays a key negative regulator of atherosclerosis progression and endothelial dysfunction, and the suppression of SIRT6 in vascular smooth muscle cells may lead to vascular calcification via impairing DNA damage repair processes." (PMID 41567643, 2025). "In addition to SIRT1, SIRT6 has been recognized for its protective roles against inflammation, vascular aging, heart disease, and atherosclerosis." (PMID 39769085, 2024). "Loss of SIRT6 in bone marrow-derived cells stimulates c-MYC transcription, thereby enhancing macrophage scavenger receptor 1 (Msr1) levels and increasing oxidized low-density lipoprotein to enhance foam cell formation and atherosclerosis." (PMID 39372420, 2024). "Sirt6 overexpression in atherosclerosis promotes macrophage autophagy and inhibits the expression of vascular cell adhesion molecule-1 (VCAM-1), ICAM-1, and platelet selectin (P-selectin), leading to reduced macrophage infiltration of macrophages and plaque stabilization." (PMID 39372420, 2024). "Taken together, results from updated studies shed new light on a possible therapeutic target of Sirt6, which may restore dysregulated lipid homeostasis and hamper atherosclerosis progression." (PMID 37497437, 2023). "The innovative research revealed that modulating Sirt6’s function in lipid metabolism might be a useful therapeutic approach for treating atherosclerosis." (PMID 37736721, 2023). "In addition, Sirt6 interacts with SNF2H as a novel regulator during atherosclerosis, inhibits Wnt1/β-catenin signalling and promotes lipid degradation." (PMID 37736721, 2023). "Our findings suggest that LKB1 may modulate VSMC-derived foam cell formation and atherosclerosis via the phosphorylation and activation of SIRT6." (PMID 37607939, 2023). "Because it is generally accepted that hyperglycemic state is one of the risk factors sensitizing patients to develop atherosclerosis, so it seems plausible that endothelial Sirt6 may influence the regulation of atherosclerosis." (PMID 37497437, 2023). "Conversely, under oxidative stress, which constitutes another crucial pathological milieu in atherosclerosis, SIRT6, by means of removing the H6K3Ac modification at the promoter of the hydrogen peroxide scavenger enzyme, suppresses the expression of said enzyme at the transcriptional level." (PMID 37981648, 2023). "Therefore, to better quest Sirt6 implication in atherosclerosis, a more suitable in vitro model should be employed in future studies." (PMID 37497437, 2023).
atherosclerosis (continued). "Interestingly, a peculiar study reported that Sirt6 also plays a deleterious role in atherosclerosis pathogenesis." (PMID 37497437, 2023). "Moreover, Sirt6 knockdown speeds up cell senescence and activates NF-κB, unveiling a vital role of Sirt6 on inflammation and thus atherosclerosis." (PMID 37497437, 2023). "Isoliquiritigenin, a licorice extract, attenuated TNF-α-induced NLRP3 inflammasome activation and pyroptosis in human umbilical vein endothelial cells by targeting sirtuin-6, which could be beneficial in the management of atherosclerosis." (PMID 37765019, 2023). "Sirt6 exhibits anti-atherosclerotic effect, and may become possible therapeutic targets for atherosclerosis treatment, together with acute coronary syndrome." (PMID 37497437, 2023). "As shown by these findings, Sirt6’s expression may be related to lipid accumulation in macrophages, it is involved in the progression of atherosclerosis." (PMID 37736721, 2023). "In addition, SIRT1 and SIRT6 also alleviated senescence in ECs and EPCs, suggesting a protective role in modulating atherosclerosis." (PMID 35569818, 2022). "A previous in vitrostudy showed that SIRT6 regulates VSMCs to switch their phenotypes from a quiescent contractile phenotype to a synthetic phenotype, which may also contribute to the function of SIRT6 in atherosclerosis." (PMID 35855341, 2022). "Thus, SIRT6 is an ideal target for treating atherosclerosis and hypertension because the roles of SIRT6 in each type of vascular cell protect the vascular tissues." (PMID 35855341, 2022). "Moreover, SIRT6 plays essential roles in protecting vessels and heart from endothelial dysfunction, atherosclerosis, pathological cardiac hypertrophy, myocardial fibrosis, heart failure and ischemia/reperfusion (I/R) injury." (PMID 36465178, 2022). "Moreover, SIRT3 and SIRT6 have been shown to play significant roles in protecting the vasculature against atherosclerosis." (PMID 35677446, 2022). "Our data support the following model for how VSMC SIRT6 regulates atherosclerosis." (PMID 33353368, 2021). "Restoring SIRT6 levels in VSMCs attenuates atherosclerosis and preserves several features of plaque stability, indicating that protecting telomere damage and increasing SIRT6 represent novel targets for both prevention and treatment of atherosclerosis in humans." (PMID 33353368, 2021). "SIRT6 inhibits atherosclerosis by deacetylating H3K9 on the promoter of the TNFSF4 gene." (PMID 33855020, 2021). "Here we focus on the involvement of SIRT6 in atherosclerosis and endothelial cell dysfunction." (PMID 33855020, 2021). "Restoring SIRT6 levels in VSMCs protects against atherosclerosis, plaque cell senescence, and inflammation and preserves features of plaque stability, revealing a therapeutic potential of SIRT6 in atherosclerosis." (PMID 33353368, 2021). "Indeed, using an in vitro model, Sirt6 reduced the formation of foam cells through an autophagy-dependent pathway, thus suggesting the protective role of Sirt6 in preventing atherosclerosis." (PMID 33467601, 2021). "Conversely, a heterozygous Sirt6 deletion (Sirt6+/−) was shown to be compatible with mouse survival and yet to produce biologically relevant effects, including enhancing adhesion molecule expression and exacerbating atherosclerosis." (PMID 33482921, 2021). "The silencing of the key autophagy initiation gene ATG5 reversed the autophagy-promoting effect of SIRT6 with an increase in foam cells, which implied an autophagy-dependent pathway of SIRT6 in protecting against atherosclerosis by reducing foam cell formation." (PMID 33855020, 2021). "SIRT6 (Sirtuin 6) is a deacetylase protein that has multiple effects on cell proliferation, death, inflammation, and metabolism, all of which are altered in cell senescence and atherosclerosis." (PMID 33353368, 2021). "As such, SIRT6-mediated autophagy plays a protective role in preventing atherosclerosis." (PMID 31492861, 2019).
atherosclerosis (continued). "SIRT6, which is highly expressed in the heart, plays a protective role in several cardiovascular-related diseases, including cardiac hypertrophy, heart failure, atherosclerosis, myocardial hypoxic damage, and metabolism." (PMID 28659816, 2017). "Here we show that SIRT6 protects against endothelial dysfunction and atherosclerosis." (PMID 27249230, 2016). "To determine whether Sirt6 is involved in atherosclerosis, we assessed the Sirt6 expression levels in atherosclerotic plaques from patients undergoing carotid endarterectomy and in carotid arteries of controls." (PMID 27045575, 2016). "As SIRT6 plays crucial roles in cellular senescence, genome integrity, and lipid metabolism and improves hypercholesterolemia and atherosclerosis, we speculated that the SNPs within the SIRT6 gene might influence the susceptibility and severity of CAD as well." (PMID 27118880, 2016). "However, the role of SIRT6 in regulating endothelial function and atherosclerosis remains poorly defined." (PMID 27249230, 2016). "Recent studies have demonstrated the critical roles of SIRT6 in DNA damage repair, lipid metabolism, and atherosclerosis, providing evidences that SIRT6 may play an important role in the CAD pathogenesis." (PMID 27118880, 2016). "For insight into mechanisms for Sirt6 heterozygosity exacerbated atherosclerosis, we investigated blood pressure, serum glucose and lipid level and body weight in ApoE−/− mice and Sirt6+/−ApoE−/− mice, which were fed with Western diet for 16 weeks." (PMID 27045575, 2016). "The protective role of Sirt6 makes Sirt6 a potential target in preventing atherosclerosis." (PMID 27045575, 2016). "However, the role of SIRT6 in regulating vascular endothelial function and atherosclerosis is not well understood." (PMID 27249230, 2016). "Because most of SIRT6 knockout mice die at 4 weeks of age, we used SIRT6 heterozygous (SIRT6+/−) mice to study whether SIRT6 haploin-sufficiency affects endothelium-dependent vasorelaxation and atherosclerosis." (PMID 27249230, 2016). "Our results provide direct in vivo evidence that Sirt6 is involved in atherosclerosis development." (PMID 27045575, 2016). "We herein show for the first time that the loss of ITCH results in a reduced development of atherosclerosis coupled with reduced hepatic fatty infiltration in the hypercholesterolemic ApoE−/− mouse model through reduced clearing of SREBP2 and SIRT6 respectively." (PMID 25777360, 2015). "It is, therefore, tempting to speculate that activators of SIRT6 might be an effective strategy for a number of inflammatory vascular diseases such as diabetes and atherosclerosis." (PMID 23132960, 2012). "Moreover, SIRT6 was recently found to deacetylate Caveolin‐1, thereby decreasing the transcytosis through endothelial cells of low‐density lipoprotein and delaying the onset of atherosclerosis in diabetic mice." (PMID 39215785, 2025). "SIRT6 activation might be a useful therapy option for atherosclerosis." (PMID 39062982, 2024). "Thus, modulating Sirt6’s function in lipid metabolism might be a useful therapeutic approach for treating atherosclerosis." (PMID 37736721, 2023). "In short, SIRT6 inhibits HIF-1α degradation to stimulate angiogenesis-related signaling pathways, revealing the cardiovascular risk associated with SIRT6 expression and suggesting that SIRT6 knockout is a feasible route to inhibit the development of atherosclerosis." (PMID 36061546, 2022). "In other types of immune cells, SIRT6 may also be necessary for preventing atherosclerosis." (PMID 35855341, 2022). "Thus, by inhibiting VSMC senescence, SIRT6 could also prevent the deleterious inflammatory and metabolic phenotype of senescence that could further promote atherosclerosis." (PMID 33353368, 2021).
atherosclerosis (continued). "Given the large amount of literature implicating endothelial dysfunction in disease contexts ranging from aging to atherosclerosis to hypertension, our data suggest that activators of SIRT6 could represent a novel class of therapeutic compounds with broad clinical utility." (PMID 34744793, 2021). "SIRT6 polymorphisms have also been associated with increased atherosclerosis, but the mechanisms underlying any protective effect of SIRT6 against atherosclerosis, and whether VSMC SIRT6 expression or function are disrupted in human atherosclerosis are unclear." (PMID 33353368, 2021). "Due to the fact that ApoE −/− mice fed a HFD show reduced SIRT6 expression, it is of great importance to investigate in future studies whether EC-specific SIRT6 overexpression will rescue vascular inflammation and atherosclerosis development." (PMID 27249230, 2016). "Also, the model we used in this study is SIRT6 haploinsufficient mice, so the specific contributory roles of EC, SMC and macrophage derived SIRT6 in atherosclerosis development remains to be investigated using individual cell type-specific knockout mice in future studies." (PMID 27249230, 2016). "Mito-Esc and metformin delayed vascular aging and improved atherosclerosis by activating mitochondrial function and inhibiting oxidative stress and inflammation via the AMPK-SIRT1/SIRT6 axis." (PMID 41584283, 2025). "In addition, SIRT6 can also interact with apoptosis-associated speck-like protein (ASC) to inhibit its acetylation, thereby reducing the interaction between ASC and NLRP3 and inhibiting the apoptosis of endothelial cells, thereby slowing the development of atherosclerosis." (PMID 40710369, 2025). "Through negatively regulating the Lin28/Let7 signaling pathway, overexpression of Sirt6 decreased GSDMD cleavage and pyroptosis in endothelial cells, which retarded the progression of atherosclerosis." (PMID 38172884, 2024). "Therefore, SIRT6 in macrophages may prevent atherosclerosis by regulating macrophage polarization and inflammation as well as foam cell formation to inhibit the initiation of atherosclerosis and plaque instability." (PMID 35855341, 2022). "SIRT6-induced deacetylation of caveolin-1 contributes to its autophagic degradation, retarding LDL transcytosis across ECs and atherosclerosis progression." (PMID 36465178, 2022). "SIRT6 can suppress the expression of miR-33 to upregulate ABCA1 and ABCG1 expression, thereby promoting cholesterol efflux and attenuating atherosclerosis." (PMID 36465178, 2022). "SIRT6 has been shown to accelerate the clearance of serum triglycerides and LDL-C; therefore, SIRT6 exerts a protective effect against atherosclerosis through the maintenance of lipid homeostasis." (PMID 36465178, 2022). "In macrophage foam cell from atherosclerosis model, SIRT6 and key autophagy effectors (ATG5, LC3B, and LAMP1) had been observed significantly and the overexpression of SIRT6 markedly reduced foam cell formation by inducing autophagy." (PMID 33855020, 2021). "Thus, we hypothesized that SIRT6 protects against the development of atherosclerosis in mice." (PMID 27249230, 2016). "Male SIRT6+/−; ApoE−/− mice and their littermate controls male SIRT6+/+; ApoE−/− mice at 8-weeks of age were put on a HFD for 8 additional weeks to accelerate atherosclerosis development." (PMID 27249230, 2016). "In addition, Sirt6 impedes LDL transcytosis across endothelial cells and hampers atherosclerosis development by deacetylation of caveolin-1." (PMID 37497437, 2023). "The latest study concerning the interplay between Sirt6 and lipid homeostasis argued that circular RNA circ_0026218 increases Sirt6 expression and suppresses ox-LDL-induced HUVECs injury and apoptosis, thereby stalling atherosclerosis progression." (PMID 37497437, 2023).
atherosclerosis (continued). "Expression of SIRT1 and SIRT6 is decreased in atherosclerotic plaques, while overexpression of SIRT1 or SIRT6 significantly attenuated oxidized LDL‐ or palmitate‐induced VSMC senescence and inhibited atherosclerosis." (PMID 35569818, 2022). "More importantly, further studies are needed to examine the potential of SIRT6 activators such as MDL-800/MDL-811 for treating aging-related vascular diseases, such as atherosclerosis, hypertension, and stroke in humans, followed by preclinical and clinical trials." (PMID 35855341, 2022). "Thus, SIRT6 represses VSMC phenotype switching and senescence to increase plaque stability and delay the development of atherosclerosis." (PMID 35855341, 2022). "SIRT6 (Sirtuin 6) is a nuclear deacetylase involved in DNA damage response signaling, inflammation, and metabolism; however, its role in regulating VSMC senescence and atherosclerosis is unclear." (PMID 33353368, 2021). "For example, miR-34a but not miR-34b/34c has been reported to inhibit SIRT6 expression in several cell lines, and SIRT6 is a renowned inhibitor of vascular aging and atherosclerosis." (PMID 32024140, 2020). "The role of hepatic SIRT6 in atherosclerosis has not been investigated to date." (PMID 37566087, 2023). "A new study showed SIRT6 could act on and deacetylate caveolin-1 in ECs, which activated autophagic degradation of caveolin-1 and inhibited high glucose stimulated LDL transport, which further inhibited the formation of atherosclerosis in diabetes." (PMID 35677446, 2022). "In addition, SIRT6 inhibits the adhesion of monocytes to ECs by decreasing the expression of vascular cell adhesion molecule-1 (VCAM-1) and intracellular adhesion molecule-1(ICAM-1) to relieve atherosclerosis." (PMID 36465178, 2022). "Loss of SIRT6 expression is not observed upon exposure to other lipid-species suggesting that the downregulation of SIRT6 seen in VSMCs in atherosclerosis may be a more specific result of fatty acids rather than a nonspecific effect of exposure to lipids." (PMID 33353368, 2021). "SIRT6 also has a long-chain deacylase activity (reviewed in Chang et al40), such that its nonhistone targets may have distinct roles in atherosclerosis." (PMID 33353368, 2021). "In addition, SIRT6-induced macrophage autophagy in oxidized LDL-C (ox-LDL-C)-treated ECs increases cholesterol efflux and reduces macrophage infiltration, endothelial inflammation and foam cell formation, thereby attenuating the pathological development of atherosclerosis." (PMID 36465178, 2022).